BAX (BCL2 associated X, apoptosis regulator)
Diseases named in the same sentence as BAX in open-access papers (continued):
Sharing a sentence is not in itself a finding about the gene and the disease.
lymphoma (continued). "Unlike the parental cells, the BAX/BAK double knockout Eμ-Myc lymphoma cells did not die upon treatment with a low dose of APR-246 since they cannot undergo apoptosis." (PMID 36739334, 2023). "In particular, in one lymphoma (833PA) it was accompanied by overexpression of Bcl6 and in the other one (800PA) by downregulation of Bcl6, indicating a molecular heterogeneity in Patz1-dependent lymphomagenesis, sometime involving BCL6 and more often BAX." (PMID 27494852, 2016). "Moreover, the blockage of necroptosis did not protect BAX/BAK double knockout Eμ-Myc mouse lymphoma cells from killing by high doses of APR-246." (PMID 36739334, 2023). "Little LDH release was seen in the BAX/BAK double knockout lymphoma cells at the relatively low dose of APR-246, regardless of whether they expressed or lacked NINJ1, because these cells are resistant to this treatment." (PMID 36739334, 2023). "While multiple lymphoma cell lines showed modulation in the copy number of BCL2 family genes, the means by which RS4;11 199R cells lost BAX expression without a loss of the BAX gene locus is unknown." (PMID 28578655, 2017).
diabetes (25 papers, 2014 to 2025). "In support, high glucose-associated activation of BAX results in increased apoptosis of β-cells in mice on a high fat diet, while ablation of the Bax gene in islets improves diabetes." (PMID 36429063, 2022). "The application of HIIT has been demonstrated to reduce the levels of apoptotic markers Bcl2-associated X protein (BAX) and BAX/B cell lymphoma/leukemia-2 (Bcl2) in BALF of mice with type 2 diabetes mellitus (T2DM)." (PMID 40182630, 2025). "Consistent with our finding, previous studies indicated that HIIT reduced apoptosis via increasing Bcl2 and decreasing BAX expression in heart following diabetes." (PMID 38233819, 2024). "In the seminal vesicles of rats with diabetes mellitus, quercetin was reported to exert a strong anti-apoptotic effect by reducing the expression of cleaved-caspase 3 and helping to increase the BCl-2/BAX ratio." (PMID 38542468, 2024). "BAX expression was remarkably elevated in the DM group, while SA observably inhibited diabetes-induced BAX levels in gastrocnemius (P<0.01)." (PMID 35432808, 2021). "The rhGH treatment decreased the expression of the proapoptotic proteins BAX and cleaved caspase-3 and increased the expression of the antiapoptotic protein Bcl-2 in mice with diabetes." (PMID 34925693, 2021). "At the end of the experiment, ZDF rats treated with RLE showed a reduction of the diabetes-associated up-regulation of both NOX4 and the p47-phox and p22-phox subunits, and restored the BAX/BCL-2 ratio respect to ZDF rats." (PMID 32466228, 2020). "As an antigen-specific monotherapy, ADi-100 is highly efficacious in reversing elevated hyperglycemia to prevent diabetes, in which increasing apoptosis-inducing BAX content is a promising immune tolerance feature." (PMID 32143316, 2020). "In relation to the diabetic ovary, our results confirm previous observations that demonstrated activation of the intrinsic pathway through BAX as a consequence of hyperglycemia." (PMID 30192809, 2018). "Sitagliptin treatment showed an antiapoptotic effect since it was able to prevent the diabetes-induced increment of mRNA and protein BAX/Bcl-2 ratio." (PMID 24817793, 2014). "The present study showed that CNPs treatment suppresses diabetes-induced apoptosis in the testicular tissue by reducing the proapoptotic BAX gene expression and enhancing antiapoptotic Bcl-2 gene expression along with the downregulation of BAX/Bcl-2 ratio." (PMID 34458667, 2021). "While the untreated and the empty vector treated cohorts reached 100% diabetes incidence (except the mVa + BAX that reached 90%), there was a significantly lower incidence of diabetes in the ADi-100 1:2- and 1:4-treated cohorts of only 20% at 15 and 23 weeks, respectively." (PMID 32143316, 2020). "The upregulation of BAX and cleaved caspase-3 and the downregulation of BCL2 expression in db/db mice indicated increased apoptosis resulting from diabetes." (PMID 38200543, 2024). "The BAX/BCL2 expression ratio in DM-iD was also significantly higher than in DM-pD (5.0-fold vs 0.6-fold, p=0.003), suggesting higher cellular apoptotic rate only in cases of diabetes with impaired osteogenic differentiation ability." (PMID 34512554, 2021). "Here, we found that proapoptotic p75NTR–JNK–B cell lymphoma 2-associated X protein (BAX) signalling is not activated, while the TrkB–ERK–CREB pathway is substantially impaired after 7 weeks of diabetes." (PMID 31053872, 2019). "To understand the molecular pathology of modified LDL-induced retinal injury in diabetes, we explored alterations in protein markers for glial activation (GFAP), angiogenesis/vascular permeability (VEGF), ER stress (KDEL and p-eIF2α) and apoptosis propensity (BAX) in mouse retina." (PMID 27306616, 2016).
osteosarcoma (24 papers, 2011 to 2025). A usually aggressive malignant bone-forming mesenchymal neoplasm, predominantly affecting adolescents and young adults. "Knockdown of IL-13Rα2 reduced protein and mRNA levels of cyclin D1, snail, TGF-β, and BCL2, while increasing BAX expression in osteosarcoma cells." (PMID 39598436, 2024). "The osteosarcoma cell line SAOS-2 is able to upregulate BAX expression and induce apoptosis thanks to RUNX2 being triggered by BMP/SMAD signaling." (PMID 37370857, 2023). "For example, in osteosarcoma cells, CtBP1 is overexpressed and the resulting CtBP1-p300-FOXO3a complex controls the expression of two proapoptotic genes BAX and BIM7." (PMID 33613771, 2021). "Consistently, the up-regulation of BAX and suppression of Bcl-2 by sclareol has been previously reported in osteosarcoma cells." (PMID 32922496, 2020). "BAX, essential in the release of caspase 3, was reported with a strong connection with osteosarcoma." (PMID 30723510, 2019). "Increased apoptosis of osteosarcoma cells by co-treatment of olaparib and doxorubicin was associated with increased expression of cleaved PARP1, cleaved caspase 3, and BAX, and decreased expression of BCL2." (PMID 29784019, 2018). "Treatment of various osteosarcoma cells resulted in increased cellular levels of BAX and a decreasing cellular level of Bcl-2." (PMID 28773642, 2016). "The compound inhibits anthracyclin-induced apoptosis in a variety of transformed human cell lines and cell death induced by doxycycline-inducible BAX overexpression in human osteosarcoma cells." (PMID 25330150, 2014). "Through activation by BMP/SMAD signaling, RUNX2 upregulates BAX expression to induce apoptosis in studies of the osteosarcoma cell line SAOS-2." (PMID 21197465, 2011). "This is consistent with earlier studies where ouabain upregulated the expression of BAX and decreased the expression of BCL-2 in rats and in human osteosarcoma cells." (PMID 41354896, 2025). "As previous studies revealed that intact BAX/BAK machinery is required for the anti-tumor effects of BH3-mimetics, we confirmed the expression of BAX and BAK in all tested osteosarcoma cell lines." (PMID 39497108, 2024). "Under doxorubicin treatment of U2OS and KHOS/NP osteosarcoma cells, the expression levels of cleaved PARP1, cleaved caspase 3, and BAX increased, and the expression of BCL2 decreased with the knock-down of CSNK2A1." (PMID 34359939, 2021). "A previous study has indicated that CtBP1 couples with p300 and FOXO3a to regulate the expression of BAX and BIM in osteosarcoma cells." (PMID 33613771, 2021). "Future studies will focus on the possible CtBP1 dependence of the downregulation of CDH1, BAX, BIM, and PTEN in osteosarcoma CSCs." (PMID 33391445, 2021). "When the U2OS and KHOS/NP osteosarcoma cells were treated with doxorubicin, the expression of cleaved PARP1, cleaved caspase 3, and BAX increased, and the expression of BCL2 decreased." (PMID 34359939, 2021). "Based on the analysis above, we supposed that biochanin A can suppress the proliferation of osteosarcoma and regulate the expression of BGLAP, BAX, and ATF3, which are involved in regulating DSB response, differentiation and cell death of osteosarcoma." (PMID 30723510, 2019). "In converse to the finding that RUNX2 upregulates BAX expression in the SAOS-2 cell line, nitric oxide (NO) treatment of the MG-63 osteosarcoma cell line induces RUNX2-mediated BCL2 expression, which promotes survival of the cells during oxidative stress." (PMID 21197465, 2011). "Biochanin A can effectively suppress the proliferation of osteosarcoma and regulate the expression of BGLAP, BAX, and ATF3, which may act as the potential therapeutic targets of osteosarcoma." (PMID 30723510, 2019).
osteosarcoma (continued). "Moreover, co-treatment of siRNA for PARP1 and doxorubicin stimulated apoptotic signaling of osteosarcoma cells as indicated by an increase of cleaved PARP1 and BAX and a decrease of BCL2 expression." (PMID 29784019, 2018). "In contrast, induction of these target genes was significantly lower in all osteosarcoma cell lines, in particular BAX and CDKN1A, where no induction was observed for all time points and XI-006 concentrations." (PMID 26095524, 2015). "Luteolin can inhibit osteosarcoma cell proliferation and induce apoptosis effectively in a dose dependent manner through down-regulating the expression of BCL-2, Caspase-3 and Survivin proteins levels and up-regulating the expression of BAX protein level." (PMID 25901161, 2015). "The nitric oxide (NO) treatment of the MG-63 osteosarcoma cell line was shown to enhance RUNX2-mediated BCL2 expression, which improves cell viability under oxidative stress, in contrast to results that suggested that RUNX2 upregulates BAX expression in the SAOS-2 cell line." (PMID 37370857, 2023). "Our studies demonstrated that luteolin inhibited MG-63 osteosarcoma cell proliferation and induced apoptosis effectively in a dose dependent manner through down-regulating the expression of BCL-2, Caspase-3 and Survivin proteins levels and up-regulating the expression of BAX protein." (PMID 25901161, 2015).
myeloma (16 papers, 2012 to 2026). "On the other hand, BAX was also reported to play a primary role in apoptosis induced by S63845 across several hematopoietic malignancies, including multiple myeloma, Eμ-Myc, and diffuse large B-cell lymphoma cells." (PMID 40075071, 2025). "In multiple myeloma (Multiple Myeloma, MM)), proteasome inhibitor PIs can trigger pyroptosis of myeloma cells (Myeloma cells) through the mitochondrial BAX/GSDME pathway and improve the therapeutic efficiency of multiple myeloma treatment." (PMID 40671910, 2025). "Myeloma cell death was associated with dual PI and Annexin-V positivity and increased expression of apoptotic genes, including CASP1, CASP8, CASP9, BAX, BID, and FASL." (PMID 36992311, 2023). "We then addressed the mechanism of action of DT2216 in myeloma cells with a particular attention on the activation of BAX and BAK." (PMID 37534243, 2023). "To test for cytotoxic and cytostatic effects of TriC, we measured myeloma cell proliferation (Ki‐67 staining), cell cycle (DAPI staining), and apoptosis (Annexin V/DAPI staining), and expression of the pro‐apoptotic protein, BAX protein." (PMID 39853696, 2025). "In myeloma cells, DT2216 induced apoptotic cell death and triggered BAX and BAK activation." (PMID 37534243, 2023). "Taken together, ALKBH5 inhibition could increase SAV1 m6A levels, suppressed the HIPPO signalling pathway and ultimately activates the transcription factor YAP in myeloma cells, promoted the expression of P21, PUMA and BAX, exerting an anti-myeloma effect in vivo and in vitro." (PMID 35414790, 2022). "Moreover, in multiple myeloma, MAGEA3 knockdown increases the levels of the proapoptotic proteins BAX and BIM and the cyclin-dependent kinase (CDK) inhibitor p21; this suggests that MAGEA3 represses apoptosis by regulating BAX, BIM, and p21, and induces cell proliferation." (PMID 34202157, 2021).
acute myeloid leukemia (15 papers, 2018 to 2025). Acute myeloid leukemia (AML) is a group of neoplasms arising from precursor cells committed to the myeloid cell-line differentiation. "In fact, in acute myeloid leukemia and non-Hodgkin lymphoma, highly expressed BAX is also associated with poor outcome." (PMID 36212143, 2022). "Upregulation of BAX, downregulation of Bcl-2 and increase in DNA fragmentation in acute myeloid leukemia." (PMID 35664773, 2022). "The study of Poeta was focused on the BAX/Bcl-2 ratio as a predictive marker for acute myeloblastic leukemia." (PMID 29515335, 2018). "Similarly, the downregulation of BAX and Phorbol-12-myristate-13-acetate-induced protein 1 (NOXA), other pro-apoptotic proteins, has been linked to resistance in acute myeloid leukemia (AML)." (PMID 39757310, 2025). "Moreover, the interaction with VDAC2 is critical for BAX to mediate cell death in response to chemotherapeutic agents both in vitro and in vivo, as well as for BAX to limit tumor development in a cMyc-driven model of acute myeloid leukemia (AML)." (PMID 30478310, 2018). "We observed lost BAX protein expression in ALL cells with acquired but not intrinsic VEN-resistance, in line with a report on pathogenic BAX mutations in acute myeloid leukemia cases with acquired resistance after VEN therapy but not in primary VEN-refractory patients." (PMID 38961053, 2024). "This includes human granulosa cells, murine macrophages, and acute myeloid leukemia cells, to name a few, supporting that BPA likely induces apoptosis predominantly through the intrinsic pathway by influencing the levels of BAX to BCL-2 proteins present around the mitochondria." (PMID 36387888, 2022). "We analyzed the expression of BCL2, BAX, and ABCB1 in bone-marrow samples collected at diagnosis from 51 adult patients with acute myeloid leukemia with normal karyotype (AML-NK) using real-time polymerase chain reaction method, and examined their prognostic potential." (PMID 37078709, 2023).
bladder cancer (14 papers, 2003 to 2025). "It has been implicated in various cancers, such as bladder cancer, and in CRC, where it interacts with genes such as BAX and BCL2." (PMID 39408697, 2024). "On the other hand, the knockdown of CHOP in bladder cancer can partly reverse the pro-apoptotic effect exerted by cytotoxic drugs through blocking the translocation of BAX from the cytoplasm to the mitochondria." (PMID 34136492, 2021). "Previous studies demonstrated that the expression level of BAX provided the prognostic information of patients with bladder cancer." (PMID 33842349, 2021). "Moreover, the miR-221 regulates Bcl-2 and BAX proteins, enhances the BAX protein level, and inhibits Bcl-2 while silencing the miR-221 in bladder cancer." (PMID 36232606, 2022). "However, the results of the present study reveal a positive correlation between the expression levels of BCL2 and BAX genes in bladder cancer." (PMID 25295115, 2014). "In the T24 bladder cancer cell line, THP treatment significantly increased the expression of apoptosis-related proteins, such as BAX, cleaved caspase-3, caspase-8, and caspase-9, while the expression level of anti-apoptotic protein BCL-2 was inhibited." (PMID 37173953, 2023). "The expression levels of BAX and BCL-2 are similar to those in human bladder carcinoma cells exposed to Brazilian red propolis." (PMID 34083947, 2021). "In bladder cancer, ERS activates CHOP and GADD34, which then trigger early apoptotic changes, including the dimerization of pro-apoptotic protein BAX." (PMID 34136492, 2021). "In this paper, 44 patients of bladder cancer are examined for MSI at BAT-26, BAT-40, TGFbRII, IGFIIR, BAX, & hMSH3 & D2S123, D9S283, D9S1851 & D18S58 dinucleotide repeat motifs." (PMID 15647110, 2005). "We believe that analysis of molecular markers such as BAX, BCL2, CD40 and CD40L may prove valuable in identifying patients with poor prognosis bladder cancers who may benefit from aggressive treatment and this should be considered in future trial design." (PMID 12592374, 2003).